MIF (macrophage migration inhibitory factor)
Diseases named in the same sentence as MIF in open-access papers (continued):
Sharing a sentence is not in itself a finding about the gene and the disease.
cancer (continued). "Recent studies indicate that MIF leads to HIF-1α activation under hypoxic conditions leading to enhancement of cancer growth and metastasis." (PMID 26530123, 2015). "It plays a role in a variety of cancer types, and has been linked with cancer cell proliferation and metastasis to bones and lymph nodes through both CXCL12 and MIF." (PMID 26347749, 2015). "Another noteworthy observation was the expression of MIF by MTFs, since MIF plays critical roles with M2 polarized macrophages, the TME, and it has been implicated in diverse pathways involved in cancer progression." (PMID 26267609, 2015). "Taken together, these studies provide experimental evidence of the potency of the MIF inhibitors in multiple cancers including GBC." (PMID 26530123, 2015). "Increasing evidence have suggested that MIF can function differently in intracellular and extracellular spaces of macrophages, both of which correlate to cancer development and metastasis." (PMID 25799489, 2015). "The findings of this study and those of others elucidates the role of MIF as a therapeutic target in multiple cancers including GBC." (PMID 26530123, 2015). "MIF has also been shown to play a role in cell proliferation where it has been suggested to be involved in the development and progression of cancer, acting as an extracellular, pro-tumourigenic factor." (PMID 25168062, 2014). "Small-molecule inhibitors of host- and cancer cell-derived MIF have been used to block its activity." (PMID 25050663, 2014). "The macrophage migration inhibitory factor (MIF) was one of the first cytokines to be described and has since been implicated in many diseases including infectious diseases and cancer." (PMID 24406307, 2014). "A more attractive approach to decrease MIF upregulation is the utilization of small molecule MIF inhibitors, which advantageously block the activity of both cancer cell- and host cell-secreted MIF." (PMID 25050663, 2014). "Several studies have identified MIF overexpression in tumors when compared with healthy tissues, and high MIF concentrations were detected in the serum of cancer patients when compared with healthy controls." (PMID 25289107, 2014). "Supporting this notion, a previous study of melanocytic tumours showed MIF mRNA and protein levels were high in malignant tumours while expression was significantly lower in benign naevi." (PMID 25168062, 2014). "Macrophage migration inhibitory factor (MIF) is a pleiotropic pro-inflammatory cytokine, which possesses a contributing role in cancer progression and metastasis and, thus, is now considered a promising anticancer drug target." (PMID 25050663, 2014). "MIF has been considered to present an important link between inflammation and cancer due to its pro-inflammatory role, overexpression in various tumor tissues and interactions with pathways that aid tumor progression." (PMID 25289107, 2014). "MIF has also been noted to circulate at elevated levels in a number of cancer subtypes, including ovarian, colorectal, breast, and prostate cancer." (PMID 25328446, 2014). "MIF treatment of N87 cells also showed increased Akt phosphorylation as control cancer cells, which was decreased upon removal of MIF." (PMID 24887129, 2014). "Since the discovery of MIF almost 50 years ago, more recent work has identified MIF as a key factor in the development and progression of human cancers, and particularly in the metastatic potential of colorectal and lung tumors." (PMID 23522304, 2013). "Among these molecules, macrophage migration inhibitory factor (MIF) is emerging as an important regulator of inflammation in cancer." (PMID 23409183, 2013). "Higher MIF levels are found in many human cancers and inflammatory diseases, including chronic pancreatitis and PDAC." (PMID 24084722, 2013). "Several studies have reported that the expression of MIF was upregulated in malignant tumors, and correlated with its aggressiveness and metastatic potential by promoting cell growth and invasion." (PMID 24138931, 2013).
cancer (continued). "MIF levels are higher at sites of inflammation, within immune and brain cells and various cancer cells." (PMID 22973314, 2012). "Serum levels of MIF are correlated with disease severity in patients with sepsis, cancer, or autoimmune diseases." (PMID 22629429, 2012). "In the presence of MIF inhibitor, ISO-1, or diminished MIF expression by shRNA transfection led to decreased autophagy in these stressed cancer cells." (PMID 22629429, 2012). "Since it is involved in the pathogenesis of acute and chronic inflammation, neoangiogenesis, and cancer, MIF and its signaling components are considered suitable targets for therapeutic intervention in several fields of medicine." (PMID 22973314, 2012). "Later, MIF was shown to contribute to neuroendocrine modulation, as a pituitary gland-derived hormone, inflammation, atherosclerosis, cancer development, and cancer progression." (PMID 22973314, 2012). "Because MIF is an important regulator of inflammation and given the established link between chronic inflammation and cancer, recent studies have examined the link between Mif mRNA expression and/or MIF protein levels and cancer." (PMID 22168770, 2011). "In cancer, miR-451 has been reported to down-regulate macrophage migration inhibitory factor, MIF, and multi-drug resistance 1, MDR1, and consequently rendering MCF7 cells more sensitive to the chemotherapeutic agent doxorubicin." (PMID 20976003, 2010). "The top protein for both normal vs. cancer and normal vs. benign was macrophage migration inhibitory factor (MIF), a known inflammatory agent." (PMID 19476629, 2009). "A good candidate for the dominating biological effect is inflammation, since the top protein selected for both normal vs. cancer and normal vs. benign was macrophage migration inhibitory factor (MIF), which is active in inflammation." (PMID 19476629, 2009). "In contrast, Bando and colleagues in their cohort of 93 primary cancer tissues predominantly observed nuclear MIF staining." (PMID 19602265, 2009). "Our preliminary results from in vitro studies need to be followed by well-designed animal studies to further evaluate MIF function in cancer progression and in response to standard treatment." (PMID 20038293, 2009). "The classification tasks of normal vs. cancer and normal vs. benign selected the same top feature: MIF, which suggests that the biomarkers indicated inflammatory response rather than cancer." (PMID 19476629, 2009). "Meanwhile, it has been appreciated that MIF constitutes an important link between chronic inflammation and cancer." (PMID 19602265, 2009). "Studies of the role of the cytokine macrophage-migration-inhibitory-factor (MIF) in malignant tumors have revealed its stimulating influence on cell-cycle progression, angiogenesis and anti-apoptosis." (PMID 20038293, 2009). "MIF is expressed in various malignant tumors, comprising ectodermal, mesenchymal and endodermal cell types." (PMID 20038293, 2009). "MIF's mechanism of action reinforces the functional connection between DNA damage, genomic instability and cancer." (PMID 17640378, 2007). "Recent publications have suggested that MIF expression can lead to increased angiogenesis which is integral to cancer growth, invasion and metastasis." (PMID 17650334, 2007). "The important role of MIF in inflammation indeed suggests that it is not only promoting existing tumors, but also likely of great relevance for the initiation of cancer by chronic inflammatory processes." (PMID 17640378, 2007). "Here, we discuss the mechanisms by which MIF affects the ubiquitin-proteasome system, and how this impacts on the integrity of the genome and on cancer." (PMID 17640378, 2007).
cancer (continued). "Cancer cells have demonstrated an increase in invasive capacity when exposed to recombinant MIF or co-cultured with macrophages leading to a TNF-α dependant increase in MIF expression via an NFκ-B pathway." (PMID 17650334, 2007). "At 20 weeks when cancer was present, increased intensity of MIF staining was noted in WT treated specimens relative to earlier specimens and to WT untreated specimens." (PMID 17650334, 2007). "MIF mRNA was observed in the cytoplasm of all prostatic epithelia, but was increased in matched cancer samples." (PMID 16000172, 2005). "Increased MIF mRNA was detected in the matched cancer samples, which was localized to the cytoplasm with some evidence of nuclear or perinuclear localization of the signal." (PMID 16000172, 2005). "MIF mRNA was localized to prostatic epithelium in all samples, but cancer showed statistically greater MIF expression." (PMID 16000172, 2005). "To establish conclusive evidence regarding the role of MIF in promoting cancer stem-like properties, we conducted experiments using tumor tissues obtained from three distinct groups: the ND group, the CDAHFD group, and the CDAHFD group with hepatic Mif knockdown." (PMID 41545340, 2026). "This modification blocks MIF-dependent downstream signaling and suppresses cancer stem cell traits." (PMID 41472252, 2025). "Consequently, MIF represents a selective and actionable therapeutic target, highlighting its potential as a promising opportunity for anti-cancer therapies." (PMID 40835826, 2025). "In cancer cells, the absence of MIF’s nuclease activity results in increased mutations, slower DNA replication, and cell cycle delays, highlighting its role in helping cancer cells survive DNA replication stress." (PMID 41159021, 2025). "In contrast to other conventional cancers, the roles of MIF signaling activation and its mediated functions in viral oncogenesis remain largely unexplored, hindering the development of MIF-targeted strategies for the prevention and treatment of these malignancies." (PMID 41472252, 2025). "Clinically, MIF can serve as a biomarker with elevated levels in cancer patients." (PMID 41159021, 2025). "Regarding anti-cancer therapies, it is still unclear whether fully developed tumors are dependent on MIF for maintenance." (PMID 40835826, 2025). "Through systematic optimization of the immobilization of antibody molecules and the anti‐fouling strategy of the sensing interface, the sensing platform demonstrates the capability to detect trace amounts of cancer markers, such as MIF, EGFR, and GPC1, within intricate biological media." (PMID 40598854, 2025). "Therapeutically, targeting MIF has shown promise in cancer treatment." (PMID 41159021, 2025). "Moreover, MIF’s recruitment to DNA replication sites by PARP1(Poly(ADP-ribose) polymerase 1) during the S phase further emphasizes its involvement in maintaining cancer cell proliferation." (PMID 41159021, 2025). "Notably, MIF exhibits pleiotropic functions: it promotes proliferation and inhibits apoptosis across various cancer types, including CRC." (PMID 40835826, 2025). "However, as an immunomodulator, MIF also exacerbates harmful inflammation, promotes cancer metastasis and progression, and worsens disease conditions." (PMID 40867844, 2025). "The cancer cells in CCC predominately secreted ligands for pathways such as MIF and SPP1." (PMID 39149248, 2024). "Therefore, it is important to design prospective studies that examine CD74 and MIF as biomarkers of ICB response or irAE development across a broad range of cancers, irAEs, and ICB treatments to determine their generalizable use in human subjects." (PMID 38730725, 2024). "High levels of MIF predict poor survival rates in cancer patients." (PMID 38178143, 2024). "MIF is a crucial cytokine involved in the pathogenesis of cancer and inflammatory diseases." (PMID 38969982, 2024).
cancer (continued). "CD74 and MIF together encourage cell proliferation and inhibit cell death, and MIF’s role in inflammation has been recognized as an important potential player in cancer initiation and development." (PMID 38730725, 2024). "MIF enrichment in KRAS-mutated CRC cell lines contributes to aberrant proliferative signaling, highlighting its potential as a target in treatment-resistant cancers." (PMID 38732068, 2024). "Nevertheless, immunosuppressive signaling interactions were also elevated; for example, immunosuppressive prostaglandin E2 (PGE2), macrophage inhibitory factor (MIF), and midkine (MK) were elevated between cancer basal cells and CD4 and CD8 T cells in the older cohort." (PMID 39483921, 2024). "Specifically, the identification of strategies that impact multiple pro-cancer phenotypes regulated by MIF could result in a more effective therapeutic response." (PMID 39233830, 2024). "Clinical trials exploring MIF targeting in cancer are limited but show promise." (PMID 38732068, 2024). "Thereby, CD74 is critically involved in MIF-driven immune cell recruitment and activation of a variety of cellular responses, including cell proliferation and cell metabolism that have been found to play a role in cancer, metabolic and ischemic heart disease." (PMID 38992165, 2024). "In addition, we depleted MIF in MAPK4-depleted BGC-823 cells in a coculture system of cancer cells and BMDMs." (PMID 36797541, 2023). "In addition, MIF was shown to correlate with the increased epithelial-to-mesenchymal transition (EMT) of the cancer cells." (PMID 36672343, 2023). "MIF is a pro-inflammatory cytokine found in macrophages, vascular endothelial cells, tissue epithelial cells, and cancer cells and influences innate immunity via TLR4 by recruiting immune cells to inflammatory locations, activating inflammatory pathways, and inducing immune cell differentiation." (PMID 37675176, 2023). "Because MIF is involved in several inflammation-related diseases, MIF inhibitors have gained great interest and, in some cases, have already been approved for treating conditions other than cancer." (PMID 36672343, 2023). "Previous studies have shown that MIF is expressed in a variety of stem cells and is involved in regulating cell proliferation and differentiation including cancer stem cells, neural stem cells, cardiac stem cells, cartilage endplate stem cells and adipose-derived stem cells." (PMID 37616250, 2023). "As an antagonist of PRG in the PRG-nPR signaling cascade, MIF certainly earned its candidacy early on as an initial therapeutic agent for the treatment of reproductive (breast, prostate, ovarian, endometrial) cancers and endometriosis, and is still on many active clinical trials." (PMID 36984647, 2023). "Further studies have shown that MIF can downregulate E-cadherin in a variety of cancer cells." (PMID 37674165, 2023). "MIF knockout mice are fertile, and their progeny develop and age normally, suggesting that MIF blockade in cancer may have limited if any systemic toxicities." (PMID 37611092, 2023). "Isothiocyanates covalently inhibit MIF, providing insights into their cancer-preventive effects." (PMID 37836558, 2023). "Moreover, as well as prolonging the survival of cancer cells, MIF and DDT can also affect the longevity of immune cells, which was shown in macrophages and neutrophils." (PMID 36672343, 2023). "Hence, MIF enzymatic tautomerase activity has attracted considerable attention and displays a novel drug target for cancer treatment." (PMID 38139858, 2023). "However, the mechanism by which MIF is regulated in cancer, particularly its secretion, remains poorly understood." (PMID 37611092, 2023). "In addition, MIF regulates the inhibition of immune responses by enhancing harmful inflammation and eventually leads to the promotion of cancer metastasis." (PMID 37091782, 2023). "MIF is a pro-inflammatory cytokine which plays a pivotal role in the pathogenesis of many cancers." (PMID 38139858, 2023).
cancer (continued). "DMBA-induced mammary gland carcinoma as marked by an elevation of mRNA level of cancer promoter genes (Serpin and MIF, LOX-1, and COL1A1) and serum level of VEGF, TNF-α, TGF-β, CA15-3, and caspase-3 with the reduction in mRNA level of suppressor gene (FST and ADRP)." (PMID 35138531, 2023). "Similarly, knockdown of FTO in TA-MSCs decreased their pro-tumorigenic effect while overexpression of FTO rescued the decreased function of cancer cells induced by MIF knockdown in TA-MSCs." (PMID 35794625, 2022). "Increased expression of MIF has been reported in diverse cancers, including NB." (PMID 35715791, 2022). "This evidence suggests that MIF is a promising target for cancer treatment." (PMID 35091838, 2022). "MIF overexpression is frequently observed in most cancers and is a poor prognostic indicator." (PMID 36703790, 2022). "In addition, it was reported that MIF expression was increased in samples of advanced cancer tissue and promoted the invasiveness of cancer cells." (PMID 35567291, 2022). "In addition, inhibition of MIF can reduce the formation of the premetastatic microenvironment in the liver and the metastasis of cancer cells." (PMID 36042480, 2022). "MIF is overexpressed and secreted in multiple cancer cells, particularly in response to hypoxia." (PMID 36042480, 2022). "MIF is a pleiotropic cytokine that plays a key role in several diseases, including cancer." (PMID 35715791, 2022). "Experiments in LNCaP sublines indicated that during neuroendocrine differentiation, although MIF synthesis decreased, MIF release significantly increased, which may promote cancer progression or recurrence especially after androgen deprivation." (PMID 36686485, 2022). "In addition, several studies investigated pathogenetic roles of MIF, and possibly D-DT, in different types of cancer, including neuro- and glioblastoma." (PMID 35688953, 2022). "Pro‐inflammatory mediators, such as MIF, promote the progression of various malignant tumours." (PMID 35567291, 2022). "Therefore, gaining a better understanding of how MIF functions will be useful for developing new therapies for various types of human cancer." (PMID 35567291, 2022). "As an immunomodulator, MIF accelerates inflammation, promotes metastasis and cancer progression." (PMID 35406551, 2022). "For example, we found that all cancer cell subpopulations express macrophage migration inhibitory factor (MIF), which could bind to CD74 receptor on the TAM and T cells." (PMID 34805184, 2021). "MIF loss in cancer cells leads to mutation frequency increases, cell cycle delays and DNA synthesis and cell growth inhibition, which can be rescued by restoring MIF, but not nuclease-deficient MIF mutant." (PMID 34012010, 2021). "Our data indicate that MIF may cooperate with Pol α to ensure the accuracy and success of the primer elongation in Pol δ- and Pol ε-proficient cancer cells." (PMID 34012010, 2021). "The macrophage migration inhibitory factor (MIF) expressed by the RMS cell line interacts with CXCR4 and CXCR7 (RMS cell surface receptors) in the paracrine loop, which can reduce the number of cancer-associated fibroblast infiltration, increase cell adhesion, and promote blood vessel formation." (PMID 34838000, 2021). "MIF plays a pleiotropic role in cancer promotion and recurrence." (PMID 34516577, 2021). "However, rSmeg-hMIF-hIL-7-infected dendritic cells significantly induced CD8+ T cells capable of killing MC38 cancer cells compared with rSmeg-hMIF or rSmeg-hIL-7, leading to decreased MIF secretion from the cancer cells." (PMID 34389619, 2021). "Furthermore, the malignant characteristics of cancer cells were suppressed by neutralizing MIF activity." (PMID 34389619, 2021). "To determine whether MIF controls DNA synthesis in cancer cells, we assessed bromodeoxyuridine (BrdU) incorporation in parental, MIF KO and its rescued cells in the S phase." (PMID 34012010, 2021). "Our data confirm elevated MIF levels in cancer cells from CRC patients." (PMID 33542244, 2021).